S100A7 (S100 calcium binding protein A7)
Diseases named in the same sentence as S100A7 in open-access papers (continued):
Sharing a sentence is not in itself a finding about the gene and the disease.
cervical carcinoma (12 papers, 2014 to 2025). A carcinoma arising from either the exocervical squamous epithelium or the endocervical glandular epithelium. "Furthermore, we investigated the biological functions and the underlying molecular mechanism by overexpression of S100A7 in cervical cancer cells." (PMID 28212564, 2017). "Thus, our study implicated that S100A7 played an important role in the pathogenesis of cervical cancer and S100A7 might be a novel valuable therapeutic target for cervical cancer." (PMID 28212564, 2017). "Cervical cancer-derived S100A7 showed a chemotactic effect on neutrophils and promoted NET generation by increasing ROS concentration." (PMID 40391215, 2025). "S100A7 was also found upregulated in tumors of the mucosa, such as cervical cancer, esophageal squamous cell carcinoma, or oral squamous cell carcinoma." (PMID 38892279, 2024). "Similar to S100A14, the expression of S100A7 was also significantly upregulated in cervical cancer tissues compared with normal cervical tissues." (PMID 36230965, 2022). "S100A7, which was expressed highly by 3DBPS with cSCC, is known to promote migration, invasion, and metastasis of cervical cancer and is highly expressed in human cSCC." (PMID 32676161, 2020). "The role of S100A7 in the metastasis of cervical cancer has been well documented in an earlier report." (PMID 31731716, 2019). "In this study, we examined the functions of S100A7 by lentiviral-mediated overexpression in cervical cancer cells." (PMID 28212564, 2017). "We set out to investigate the potential role of S100A7 in the development of a malignant phenotype in cervical cancer cells by modulating intracellular S100A7 expression." (PMID 28212564, 2017). "Our studies demonstrated that S100A7 promoted cervical cancer cell migration and invasion as a secreted chemotactic factor." (PMID 28212564, 2017). "We firstly examined mRNA and protein expression levels of S100A7 in the four common cervical cancer cells including C33A, HeLa, SiHa and CaSki and found that S100A7 was expressed at a low level in the four cell lines." (PMID 28212564, 2017). "Our data indicated immunoactivity of S100A7 on cervical cancer tissues correlates with tumor grade and lymph node metastasis, and S100A7 was involved in cervical carcinogenesis by promoting migration, invasion, metastasis and epithelial-mesenchymal transition." (PMID 28212564, 2017). "Functional studies showed that overexpression of S100A7 in cervical cancer cells promoted migration, invasion and metastasis of cervical cancer cells without influencing cell proliferation." (PMID 28212564, 2017). "The results demonstrated that S100A7 overexpression dramatically promoted cell migration, invasion and metastasis of cervical cancer cells." (PMID 28212564, 2017). "In this study, we showed that S100A7 was secreted in the supernatant of S100A7-overexpressing cells and conditioned media of S100A7-overexpressing cells enhanced migration and invasion of cervical cancer cells." (PMID 28212564, 2017). "In the present study, we firstly detected the expression of S100A7 in cervical cancer tissues and analyzed the correlation between S100A7 expression and clinicopathologic characteristics." (PMID 28212564, 2017). "S100A7 is reported to promote migration, invasion and metastasis of human cervical cancer cells through epithelial-mesenchymal transition (EMT) but the activation signaling of S100A7 is unknown." (PMID 31731716, 2019). "S100A7 is differentially up-regulated in three of six cervical cancer patients." (PMID 31731716, 2019). "These phenomena led us to hypothesize that S100A7 may also be involved in the migration/invasion of cervical cancer cells." (PMID 28212564, 2017). "S100A7 overexpression in cervical cancer may also be due to inflammatory cytokines stimulation, which needs further investigation in the future." (PMID 28212564, 2017). "S100A7 expression was higher in cervical cancer tissues than that in normal tissues (P < 0.01)." (PMID 28212564, 2017).
cervical carcinoma (continued). "Moreover, S100A7 expression was increased in high grade CIN compared with cervical cancer (P < 0.01)." (PMID 28212564, 2017). "However, information is limited about the possible biologic significance of the altered expression of S100A7 during cervical cancer development." (PMID 28212564, 2017). "Present data extend prior work and indicate that S100A7 drives upregulation of EMT markers N-Cadherin, Vimentin, and Fibronectin and loss of epithelial markers E-cadherin, thereby inducting EMT, promoting cervical cancer cell migration and invasion by inducing EMT." (PMID 28212564, 2017). "Furthermore, knockdown of RAGE by siRNA transfection significantly suppressed S100A7-induced cell migration and invasion, indicating that S100A7 promotes cervical cancer cell migration and invasion at least partially through RAGE." (PMID 28212564, 2017). "On the basis of the IHC analysis of S100A7 expression in cervical cancer, we speculate that S100A7 plays an important role in tumorigenesis and cancer progression." (PMID 28212564, 2017). "Moreover, S100A7 expression is higher in cervical cancer compared with normal cervical tissue." (PMID 28212564, 2017). "However, the role of S100A7 in cervical cancer and its underlying molecular mechanisms are still not clarified." (PMID 28212564, 2017). "S100A7 protein plays a role in regulating cell migration, invasion, metastasis and EMT of cervical cancer." (PMID 40391215, 2025). "There are many subtypes of S100 calcium-binding protein, and several studies have found that S100A7, S100A9, S100A11, and S100A14 are closely related to cervical cancer." (PMID 36230965, 2022). "In summary, our present research showed that S100A7 induces EMT and promotes cell migration, invasion and metastasis of cervical cancer cells." (PMID 28212564, 2017). "Overexpressing S100A7 in cervical cancer cells promoted their migration and invasion without affecting their proliferation." (PMID 38499391, 2024). "In summary, these data reveal a crucial role for S100A7 in regulating cell migration, invasion, metastasis and EMT of cervical cancer and suggest that targeting S100A7 may offer a new targeted strategy for cervical cancer." (PMID 28212564, 2017). "However, the correlation between S100A7 expression and clinicopathological features in cervical cancer has not been studied." (PMID 28212564, 2017).
lung cancer (11 papers, 2011 to 2025). A malignant neoplasm involving the lung. "For instance, S100A12 generally shows low expression in lung cancer, while S100A7 is more specific to squamous and large cell carcinomas, but not adenocarcinomas or small cell lung cancer." (PMID 40735471, 2025). "The S100A7 expression is induced by activation of the Hippo pathway and acts as a facilitator in the adenosquamous transition of lung cancer cells." (PMID 34239729, 2021). "Lu et al28 observed that TBILA (TGFβ‐induced lncRNA) promoted HGAL expression and bound with S100A7 to enhance its carcinogenic effects in non‐small cell lung cancer." (PMID 32583631, 2020). "Knockdown of S100A7 attenuated lung cancer growth by disruption of nuclear factor-κB activity, and S100A7 was reported as a potential diagnostic marker in lung squamous cell carcinoma." (PMID 29607329, 2018). "Here, we demonstrated that S100A7 not only promotes lung ADC to SCC transdifferentiation in several lung cancer cells but also that its expression is differentially regulated by the Hippo-YAP pathway." (PMID 28177901, 2017). "Here, we verify that S100A7 acts as a facilitator of adenous-squamous phenotypic transition in lung cancer cells." (PMID 28177901, 2017). "In conclusion, our results demonstrate that S100A7 not only facilitates ADC to SCC transdifferentiation in lung cancer cells but also elicits a distinct response to Hippo-YAP regulation." (PMID 28177901, 2017). "Although the latent differentiation program of cancer cells is commonly repressed in vitro, our results provide direct evidence that lung ADC to SCC transdifferentiation is successfully rescued by S100A7 overexpression in several lung cancer cell lines." (PMID 28177901, 2017). "Knockdown of S100A7 suppresses lung cancer growth in part by attenuating NF-κB activity, and S100A7 promotes the migration and invasion of osteosarcoma cells and enhances the activity of MMP2 and MMP9 through RAGE." (PMID 28212564, 2017). "And the level of S100A7 protein in serum may serve as a potential marker in lung cancer and ovarian cancer." (PMID 28212564, 2017). "We further demonstrate that S100A7 is not only induced by activation of the Hippo pathway but also that its overexpression partially rescues squamous differentiation inhibited by YAP overexpression in several lung cancer cells." (PMID 28177901, 2017). "Therefore, it would be interesting to investigate the relationships and functions of YAP and S100A7 in other cancers, such as lung cancer." (PMID 28177901, 2017). "However, accumulating evidence suggested that S100A7 was negatively correlated with immune infiltration and immunomodulators in the lung cancer, for instance, expression of S100A7 could inhibit PD-L1, leading to down-regulating CD68+ macrophage infiltration." (PMID 38499391, 2024). "However, several studies suggest that S100A7 may have a role in several respiratory diseases, including lung cancer, asthma, rhinosinusitis, pulmonary complications of systemic sclerosis, and bacterial exacerbations." (PMID 34239729, 2021). "However, little is known about how and why S100A7 induction occurs in lung cancer cells." (PMID 28177901, 2017). "Thus, understanding the mechanisms of S100A7 induction in lung cancer might have important implications for S100A7-targeted therapies." (PMID 28177901, 2017). "Regarding the role of S100A7 in lung cancer, it was shown that this protein is highly expressed in lung squamous cell carcinoma (SCC), an NSCLC subtype, and that knockdown of S100A7 resulted in decreased NF-κB-dependent cell proliferation." (PMID 32722137, 2020). "Thus far, the functions of S100A7 in lung cancer have remained largely unknown." (PMID 28177901, 2017). "Considering the opposite effects of YAP and S100A7 on lung ADC to SCC transition, we further investigated the relationship of these two proteins in lung cancer cells." (PMID 28177901, 2017).
lung cancer (continued). "Additionally, a high level of S100A7 was correlated with poor OS, first progression (FP), and PPS prognosis for lung cancer and gastric cancer, as well as a poor OS and disease-specific survival (DSS) for liver cancer but not ovarian cancer." (PMID 35205150, 2022). "Although we are not entirely clear on how S100A7 regulates DNp63, TFF1 and napsin A expression in lung cancer cells, our findings provide a novel pathway of lung cancer phenotypic plasticity during tumor progression." (PMID 28177901, 2017).
ovarian carcinoma (11 papers, 2007 to 2024). A malignant neoplasm originating from the surface ovarian epithelium. "S100A7 was associated with poor prognosis in ovarian cancer." (PMID 38499391, 2024). "Decreased expression of KRT6A and S100A7 have been associated with breast, lung and ovarian cancer." (PMID 17543121, 2007). "Knocking down of S100A7 reduces the ability of proliferation, migration, and invasion of ovarian cancer cells." (PMID 36077500, 2022). "S100A7-knockdown ovarian cancer cells show increased sensitivity to cisplatin although the mechanism is not clear." (PMID 36077500, 2022). "By regulating cyclinD1, MMP9 and p27, knockdown of S100A7 reduces epithelial ovarian cancer (EOC) cell proliferation, migration and invasion, and enhances chemosensitivity to cisplatin." (PMID 36077500, 2022). "The prevalence of S100A7 autoantibodies in ovarian cancer patients, patients with benign gynaecological disease and healthy controls was analysed by ELISA." (PMID 21339995, 2011). "The mean plasma levels of S100A7 autoantibodies were significantly greater in both early stage and advanced stage ovarian cancer patients when compared to healthy controls." (PMID 21339995, 2011). "In particular, increased expression of S100A1, S100A4, S100A7, and S100A14 has been documented in multiple cancers including ovarian cancer." (PMID 31739800, 2019). "It has been reported that S100A7 forms a complex with FABP4 in human keratinocytes, and adipocyte-derived lipids have previously been shown to promote tumor growth by providing an energy source such as FABP4 in ovarian cancer." (PMID 28629450, 2017). "Furthermore, analysis of S100A7 autoantibodies alone or as a composite biomarker to CA125 showed that the sensitivity and specificity remained inferior to CA125 alone at detecting ovarian cancer." (PMID 21339995, 2011).
inflammatory skin disease (9 papers, 2005 to 2025). Inflammatory skin disorders covers a broad category that includes many conditions ranging in severity, from mild itching to grave medical health complications These disorders are common in people of all ages and races. "S100A7, for example, is implicated in inflammatory skin diseases and in several cancers including breast cancer where it is associated with aggressive estrogen receptor negative tumors and poor prognosis." (PMID 22747601, 2012). "S100A7 functions in the protection of the skin and mucous membranes and is a biomarker in inflammatory skin disease." (PMID 37769710, 2023). "Human psoriasin/S100A7 was originally cloned from psoriatic skin, an inflammatory skin disease." (PMID 15717926, 2005). "After analysing the RNA‐seq data, we discovered that Livin expression influenced the release of antimicrobial peptides such as S100A3, S100A7, and BD1 from KCs, which have been demonstrated to play important roles in many inflammatory skin diseases and could be increased following UVB exposure." (PMID 38332512, 2024).
atopic dermatitis (8 papers, 2008 to 2024). "The reported list of inflammatory mediators found in atopic dermatitis includes S100A7, S100A8 S100A9, CCL2, CCL3, IL36A, IL36G, and IL36RN." (PMID 34925353, 2021). "Interestingly, S100A7A is highly increased in psoriatic skin and shares near-complete homology with S100A7 (Psoriasin), which has a well-established role in the pathogenesis of psoriasis and is also increased in atopic dermatitis." (PMID 31059533, 2019). "S100A7 is overexpressed in many epidermal inflammatory diseases, including atopic dermatitis, mycosis fungoides, Darier’s disease, and inflammatory lichen sclerosus and atrophicus, suggesting that S100A7 may play a role in the inflammatory process." (PMID 24671027, 2014).
bladder cancer (7 papers, 2005 to 2024). "TISIDB analysis indicated a correlation between high S100A7 expression and adverse outcomes in bladder cancer patients, suggesting a close association with tumor progression." (PMID 38217031, 2024). "Studies of human psoriasin /S100A7 support a similar association in skin and bladder cancer." (PMID 15717926, 2005). "We selected two small interfering RNAs (siRNAs) for transfection into T24 and UMUC-3 bladder cancer cell lines to validate the impact of S100A7 on tumor cells." (PMID 38217031, 2024). "Pan-cancer analysis reveals a significant upregulation of S100A7 expression in various cancers, including bladder cancer." (PMID 38217031, 2024). "The results indicated that reducing the expression of S100A7 led to a significant inhibition of bladder cancer cell proliferation and invasion." (PMID 38217031, 2024). "In conclusion, S100A7 plays a significant role in bladder cancer, and as such, we have selected it for further experimental validation and analysis." (PMID 38217031, 2024). "These in vitro experimental findings underscore the significant role of S100A7 in tumor cell proliferation and migration, suggesting its potential as a therapeutic target in future bladder cancer treatments." (PMID 38217031, 2024). "Our pan-cancer analysis revealed elevated expression of S100A7 in various cancer cells, including bladder cancer." (PMID 38217031, 2024). "There is accumulating evidence that S100A7 is up-regulated in bladder cancer skin tumors and some invasive carcinomas." (PMID 19691830, 2009). "Additionally, our data analysis and in vitro experiments have identified a promising therapeutic target for bladder cancer treatment, namely S100A7." (PMID 38217031, 2024). "Moreover, elevated expression of S100A7 was observed in bladder cancer patients with muscle-invasive tumors, thus piquing our interest." (PMID 38217031, 2024). "In this study, we delved further into the role of S100A7 in bladder cancer cells." (PMID 38217031, 2024). "Furthermore, we conducted in-depth research into the role of anoikis-related gene S100A7 in bladder cancer, particularly its impact on cell proliferation and invasion." (PMID 38217031, 2024). "Finally, we identified that knocking down S100A7 gene expression restrained the proliferation and invasion of bladder cancer cells." (PMID 38217031, 2024). "Additionally, through cellular experiments, we demonstrated the significant role of S100A7 in the metastasis and invasion of bladder cancer, suggesting its potential as a novel target for future treatments." (PMID 38217031, 2024). "Secondly, the regulatory mechanism of S100A7 on the proliferation and migration capabilities of bladder cancer cells was not further investigated." (PMID 38217031, 2024).
esophageal squamous cell carcinoma (7 papers, 2015 to 2024). Esophageal squamous cell carcinoma (ESCC) is a type of esophageal carcinoma (EC) that can affect any part of the esophagus, but is usually located in the upper or middle third. "The results showed that 41% of lung SCCs, 76.6% of esophageal SCCs, 50.6% of cervical SCCs, 80.4% of oral SCCs, 84.8% of skin SCCs and 66.7% of bladder SCCs were positive for S100A7." (PMID 26053695, 2015). "S100A7 could promote esophageal squamous cell carcinoma progression by activating oncogenic pathways and remodeling the TME." (PMID 38049825, 2023). "Researchers have found that it was abnormally upregulated in esophageal squamous cell carcinoma (ESCC), which might promote tumor progression by impacting M2 macrophage infiltration and angiogenesis; thereby, S100A7 was expected to act as a therapeutic target for ESCC treatment." (PMID 35256894, 2022). "For example, almost all members of the S100 family were highly expressed in ESCA, consistent with previous studies demonstrating high expression of S100A7, S100A8, and S100A9 in esophageal squamous cell carcinoma (ESCC), which predicted cancer cell migration and worse overall survival." (PMID 38684596, 2024).
invasive carcinoma (6 papers, 2005 to 2024). A carcinoma that is not confined to the epithelium, and has spread to the surrounding stroma. "Some of the most significant differential mRNA expressions were found for COL1A1, SPARC, and LGALS1 that were stronger expressed in invasive carcinoma compared to high‐grade dysplasia, and the opposite was shown for S100A7, which was stronger expressed in high‐grade dysplasia." (PMID 31454186, 2019). "Other differentially expressed transcripts include S100A7, LCN2, CXCL14, and CD207 (decreasing expression from premalignant lesions to invasive carcinoma), as well as IDO1, IL6, IL8, THBS1, and FN1 (increasing expression from premalignant lesions to invasive carcinoma)." (PMID 38706595, 2024). "Consistently, other studies also showed that S100A7 expression was relatively low in normal, benign and atypical hyperplastic proliferative ductal lesions, high in the pre-invasive ductal carcinoma in situ (DCIS), but reduced in invasive carcinomas." (PMID 28212564, 2017). "S100A7 expression is relatively low in normal, benign and atypical hyperplastic proliferative ductal lesions, high in the pre-invasive ductal carcinoma in situ (DCIS), but reduced in invasive carcinomas." (PMID 20689826, 2010).